CD40 (CD40 molecule)
Diseases named in the same sentence as CD40 in open-access papers (continued):
Sharing a sentence is not in itself a finding about the gene and the disease.
Hyperglycemia (13 papers, 2014 to 2024). An increased concentration of glucose in the blood. "Hyperglycemia-induced CD40 expression in Müller glia is mediated via enhanced O-GlcNAcylation of 4 E-BP1/2, leading to neurovascular degeneration in DR." (PMID 37172821, 2023). "In detail, hyperinsulinemia and hyperglycemia can enhance CD40 levels in platelets and monocytes, whereas CD40 expression inhibition downregulated both leukostasis and ICAM-1 expression in endothelial cells." (PMID 37569354, 2023). "Fully functional CD40 expression is not only required for hyperglycemia and insulitis in T1D but also induces relatively broad T‐cell receptor repertoire on CD40+ CD4+ cells (Th40 cells) during diabetogenesis." (PMID 36704045, 2022). "Both hyperglycemia and hyperinsulinemia can increase CD40 levels in monocytes and platelets while inhibition of CD40 expression prevents both leukostasis and ICAM-1 expression in endothelial cells, as well as late capillary loss/degeneration and inflammation." (PMID 33240272, 2020). "For example, CD40 is expressed in retinal endothelial cells and Müller cells, as well as in islet β-cells during hyperglycemia." (PMID 29073149, 2017). "Moreover, this study is among the first to report the expression of CD-40 in HMG using an in vitro model of hyperglycemia, as observed in diabetic rats to highlight the significance of in vitro models using AGEs in addition to high glucose." (PMID 39596335, 2024). "BMI correlated inversely with changes of PD-L1 and CD40 during hyperinsulinemia, Oncostatin-M, TNFSF14, FGF-21 and 4EBP-1 during hypoglycemia and CCL23, VEGF-A and CDCP1 during hyperglycemia (Rho ≤ -0.50)." (PMID 37400734, 2023). "CD40, a member of the TNFR superfamily, was found to be upregulated by hyperglycemia in retinal Müller cells." (PMID 37172821, 2023). "Peptide vaccination alone or in conjunction with the administration of CpG ODN 1826, LPS, or anti-CD40 agonist antibody did not result in hyperglycemia in RIP-gp single-transgenic mice." (PMID 24647761, 2014).
type 1 diabetes (13 papers, 2007 to 2026). "As genes associated with immune-mediated diseases have an increased prior probability of being associated with other immune-mediated diseases, we tested three such genes, IL23R, IRF5 and CD40, for an association with type 1 diabetes." (PMID 18045485, 2007). "Furthermore, reduced numbers of CD40+ B cells is observed in individuals with type 1 diabetes, compared to healthy donors; however, the levels of CD40 expression on B cells were not measured in this study." (PMID 34616408, 2021). "CD4 T cells expressing CD40 (Th40) are pathogenic in type I diabetes but have not been evaluated in EAE." (PMID 28192476, 2017). "Lack of association of IL23R, IRF5 and CD40 with type 1 diabetes helps to delineate pathogenic mechanisms between type 1 diabetes and other immune-mediated diseases, especially when the associations reported for the other diseases are highly likely to be true positive results." (PMID 18045485, 2007). "One of the notable characteristics of the DC generated from monocytic progenitors in the presence of the mixture of antisense DNA targeting the primary transcripts of CD40, CD80, and CD86 used in the phase I type 1 diabetes safety trial is their ability to produce retinoic acid (RA)." (PMID 29774025, 2018). "Based on our in vitro data pointing to minimal inhibition of T cells by CD40 blockade, we propose that iscalimab may not suffice to accomplish durable benefit as intervention strategy to treat type 1 diabetes or other T cell mediated diseases." (PMID 42284279, 2026).
neuroblastoma (12 papers, 2003 to 2024). Neuroblastoma (NB) is the most common solid, extracranial childhood tumor. "Gly has been demonstrated to induce death of human neuroblastoma SH-SY5Y cells through upregulation of CD40 expression." (PMID 38297317, 2024). "When combined with multidrug chemotherapy, radiation, anti-GD2, and anti-CTLA-4, this anti-CD40 and CpG therapy exhibited potent anti-tumor effects in mice with 9464D neuroblastoma tumors, repolarizing TAMs towards an M1 phenotype." (PMID 38087370, 2023). "Other preclinical publications showed their efficacy against neuroblastoma in combination with dinutuximab beta or with radiation and an anti-CD40 antibody." (PMID 36700232, 2022). "The functional role of surface CD40 in neuroblastoma cells was investigated using both IFN-γ-treated cell lines and the ACN cell line transfected with a plasmid carrying the human IFN-γ gene." (PMID 12771917, 2003). "Agonistic anti-CD40 antibodies induce tumoricidal effects against neuroblastoma cells in vivo." (PMID 32983125, 2020). "Furthermore, the addition of HDACi trichostatin A (TSA) enhanced the expression of MHC class I and II, as well as the co-stimulatory molecule CD40 on the human neuroblastoma tumor cell line SK-N-MC." (PMID 25815463, 2015). "All CD40+ neuroblastoma cells underwent massive apoptosis following 48 h culture with CD40L." (PMID 12771917, 2003). "In the same way, sodium butyrate, a class I/IIa HDACi, and TSA activated expression of class I and II MHC and CD40 in multiple human neuroblastoma (NB) or mouse plasmacytoma J558 tumour cell lines." (PMID 28572863, 2017). "Sondel group has done intensive research on the repolarization of macrophages by the use of monoclonal CD40 mAb and cytosine-phosphate-guanosine containing oligodeoxynucleotide 1826 (CpG-ODN) (IT) in neuroblastoma models." (PMID 32722460, 2020). "Recently Sondel group has shown that CD40 mAb along with CpG and anti-CTLA4 antibody provides potent anti-tumor immune responses in immunologically cold murine syngeneic neuroblastoma murine model." (PMID 32722460, 2020). "Since Voeller and colleagues already described synergy between CD40 agonists and anti-GD2 therapy in neuroblastoma, the addition of TNF and CD40 agonists to the treatment regimen could prove a promising new strategy." (PMID 38087370, 2023). "Here, we have investigated the expression of costimulatory molecules (CD40, CD80, CD86, PD-1L, B7H2, OX40L and 4-1BBL) in human neuroblastoma (NB) cells, since virtually no information is available on this issue." (PMID 12771917, 2003). "Mice bearing disialoganglioside (GD2)-expressing neuroblastoma tumors (either NXS2 or 9464D-GD2) were treated with radiation and immunotherapy (including anti-GD2 immunocytokine with or without anti-CTLA-4, CpG and anti-CD40 monoclonal antibody)." (PMID 31810498, 2019).
hyper-IgM syndrome (11 papers, 2013 to 2024). A primary immune deficiency disorder characterized by defective CD40 signaling; via B cells affecting class switch recombination (CSR) and somatic hypermutation. "Hyper IgM syndromes are a group of primary immunodeficiency disorders caused by defects in the CD40 ligand or CD40-signaling pathway, leading to impaired B-cell proliferation, immunoglobulin class switch recombination (CSR), and germinal center formation." (PMID 39886113, 2024). "CD40, variants which can lead to hyper-IgM syndrome (HIGM3) due to impaired somatic hypermutation generating antibody variation, provides one of the central inputs for B cell activation." (PMID 30116248, 2018). "The hyper-IgM syndrome is either an inherited X-linked PID due to mutations in the gene encoding CD40 ligand or autosomal recessive PID due to mutations in CD40, AID or UNG genes." (PMID 27642394, 2016). "The discoveries of CD40L, the CD40L defects in patients with hyper-IgM syndrome and subsequent studies with CD40- and CD40L-deficient mice established the key role of CD40 in T-cell-dependent B-cell responses." (PMID 25324844, 2014). "A genetic defect in CD40, an autosomal recessive form, or its downstream signaling molecules such as activation-induced cytidine deaminase and uracil-DNA glycosylase, resulting in defects in CD40-mediated signal transduction in B cells, may also cause hyper IgM syndrome." (PMID 31426619, 2019). "Of the five patients diagnosed as having hyper IgM syndrome (HIGM), one was found to have a CD40 deficiency, which is seen in < 1% of patients with HIGM." (PMID 24373416, 2013). "In fact, genetic mutation of CD40L leads to a compromising X-linked disease called hyper-IgM syndrome, in which patients’ B cells are unable to produce other subtypes of immunoglobulins aside from the default IgM due to the absence of CD40 activation by normal CD40L." (PMID 32498446, 2020).
Hypertension (11 papers, 2011 to 2025). The presence of chronic increased pressure in the systemic arterial system. "We used different genetic mouse models of specific CD40 deficiency on adipocytes, B-, and T-cells to assess the impact on hypertension." (PMID 39899926, 2025). "In our results it presents some association with some phenotypes related with immune response (white blood count, neutrophils, CD40 or total protein) but also with some markers of ECG related with hypertension." (PMID 25329069, 2014). "In fact, our previous investigations have shown CD40 to be important in the pathogenesis of renal fibrosis and inflammation in the setting of hypertension and atherosclerotic renal artery stenosis, and actually predictive of renal function in patients with chronic kidney disease." (PMID 32498446, 2020). "The antioxidant potential of phenolic compounds associated with the increase in HDLc levels in the mice of the HLU group prevented the development of LVH and arterial hypertension since it inhibited the inflammatory response induced by the CD40 pathway and its ligand CD40L." (PMID 32881885, 2020). "Arterial hypertension was induced in WT (C57BL6/J) and cell-specific CD40(L) knockout mice (AdipoqCre x CD40 fl/fl, CD4Cre x CD40 fl/fl, CD19Cre x CD40 fl/fl, and GP1baCre x CD40L fl/fl) via angiotensin (AT-II) infusion (1 mg/kg/d) for seven days." (PMID 39899926, 2025). "Therefore, we conclude that targeting CD40 directly on adipocytes, B-cells, T-cells, or CD40L on platelets is not a promising target to prevent hypertension complications." (PMID 39899926, 2025).
malaria (11 papers, 2006 to 2023). Malaria is a serious and sometimes fatal disease caused by a parasite that commonly infects a certain type of mosquito which feeds on humans. "Increased CD40 expression associated to malaria exposure might favor aaMBC survival, as strong CD40L stimulus of GC cells has resulted in production of antiapoptotic proteins, providing survival signals rescuing the GC B cells from CD95-induced death." (PMID 28878766, 2017). "One of the important discoveries of this study is linking the CD40 protective effect to elevated IFN-I responses in this N67 malaria parasite and C57BL/6 mouse model." (PMID 27716849, 2016). "Another interesting question is how CD40 is activated by malaria ligands." (PMID 27716849, 2016). "Up-regulation of genes in IFN-I responses (ISG genes) has been associated with mild human P. falciparum malaria following an episode of severe malaria, suggesting that CD40/STING/IFN-I and other IFN-I protective mechanisms may play a role in infections of some human parasite strains." (PMID 27716849, 2016). "Moreover, in an independent experiment (n = 10 Malian children) T-bethi B cells of malaria-exposed children expressed markers that are known to be associated with atypical MBCs, with higher surface expression of FCRL5, CD11c, CXCR3 and CD95, and decreased expression of CD35, CD40, CXCR5 and CCR7." (PMID 28953967, 2017). "Here we investigated the interaction of two important host molecules, CD40 and STING, in host type I interferon (IFN-I) responses to malaria infection using a mouse malaria model." (PMID 27716849, 2016). "In this study, we identified genes related to the malaria resistance pathway (KEGG: hsa05144), including CCL2, CD40, HBA1, and HBA2 as the differential genes in DAI, indicating different selective pressure posed by malaria on the DAI compared to other M.Yunnan.West." (PMID 35864541, 2022). "Individuals highly exposed to malaria had more PD1+, CD95+, CD80+, CD71+, and CD40+ aaMBC than malaria non-exposed individuals." (PMID 28878766, 2017). "We observed higher frequencies of CD40+ aaMBCs and CD40+ acMBCs in malaria-exposed compared to non-exposed individuals, with a tendency of increased frequencies with higher exposure." (PMID 28878766, 2017). "Considering that the binding of CD40 to its ligand CD40L is critical for the production of antibodies in B cells, it is possible that this molecule is involved in the immune response against malaria." (PMID 26901523, 2016). "Here we demonstrate that MPs, derived from the plasma of malaria infected mice, but not naive mice, induce potent activation of macrophages in vitro as measured by CD40 up-regulation and TNF production." (PMID 20126448, 2010). "This study reveals previously unrecognized CD40 function in innate IFN-I responses and protective pathways in infections with malaria strains that induce a strong IFN-I response, which may provide important information for better understanding and management of malaria." (PMID 27716849, 2016). "DCs incubated with RBCs or pRBCs did not, however, increase expression of MHC class II, CD40, CD80 and CD86, indicating that malaria parasites do not induce DC activation directly." (PMID 16611373, 2006).
non-small cell lung carcinoma (11 papers, 2013 to 2025). A group of at least three distinct histological types of lung cancer, including non-small cell squamous cell carcinoma, adenocarcinoma, and large cell carcinoma. "Additionally, Kaplan–Meier progression-free survival curves for non-small cell lung cancer patients with malignant pleural effusion showed that high soluble CD40 is associated with poor prognosis (HR = 0.4643, P = 0.045." (PMID 32256143, 2020). "Consequently, we performed immunohistochemistry for CD40 and CD154 in 129 non-small cell lung cancer (NSCLC) patient tissue samples." (PMID 23404288, 2013).
psoriasis (11 papers, 2007 to 2024). An autoimmune condition characterized by red, well-delineated plaques with silvery scales that are usually on the extensor surfaces and scalp. "This trend is further supported by our sensitivity analyses, where a significant protective effect of CD40 on risk of developing psoriasis was also found." (PMID 34878845, 2021). "Polymorphisms in CD40 are associated with psoriasis, UC, CD, RA, and SLE, and CD40 is more abundant in UC colon and AD dermal samples compared to healthy controls." (PMID 39297883, 2024). "Analysis of cell surface markers expression on B cells (i.e., CD40, CD44, CD80, CD86,CD11b, and HLA-DR) is the key to understand their pathogenic role in psoriasis." (PMID 27532281, 2016). "The role of co-signaling molecules in psoriasis is recognized, mainly including the co-stimulatory molecules CD28, CD40, OX40, CD27, DR3, LFA-1, and LFA-3 and the co-inhibitory molecules CTLA-4, PD-1, and TIM-3." (PMID 34354596, 2021). "Therefore, our results confirm that CD40, CD44, CD80, and CD86 are likelyimportant in the pathogenesis of psoriasis, especially at the active stage." (PMID 27532281, 2016).
AIDS (10 papers, 2010 to 2025). A syndrome resulting from the acquired deficiency of cellular immunity caused by the human immunodeficiency virus (HIV). "The effects of the confounder change over time mean that the strength of association between CD40 and AIDS (CD40 → AIDS) is different from that of CD41 and AIDS (CD41 → AIDS)." (PMID 31619986, 2019). "Consistent with the reported loss of CD40 expressing dendritic cells in AIDS patients, this regulatory pathway attenuates leading to the lower APOBEC3 transcription, which we observed in PBMC of animals with symptoms of AIDS." (PMID 21955401, 2011). "In this work, we observed elevated levels of CD40 bearing EVs in circulation of pre-AIDS-NHL subjects, which can engage and signal activated T-cells and/or facilitate their recruitment to distant sites." (PMID 37809067, 2023). "We also found significant associations between increased levels of EVs bearing PD-L1, CD40, TNF-RII and/or IL-6Rα with AIDS-NHL risk and more specifically with the development of non-CNS AIDS-NHLs." (PMID 37809067, 2023). "Conversely, Vpu was shown to upregulate the expression of CD40 in endothelial cells, increasing cellular adhesion of B-lymphoma cells, which plays a role in the pathogenesis of AIDS-related B-cell non-hodgkins lymphoma (AIDS-NHL)." (PMID 34834972, 2021). "The results described in this study show that EVs bearing PD-L1, CD40, TNF-RII and/or IL-6Rα are significantly associated with AIDS-NHL risk and thus, may serve as biomarkers of AIDS-NHL." (PMID 37809067, 2023). "For this, we used humanized anti-CD40 or anti-DCIR antibodies coupled to Ag85BD41-ESAT6-Rv1980D24 Mycobacterium tuberculosis antigens developed by the ANRS (French agency of research against AIDS and viral hepatitis)." (PMID 23166489, 2012). "This CD40 signaling may be especially critical in eliciting CTL responses in conditions such as AIDS during which the number or activity of CD4+ T cells is limited." (PMID 21592361, 2011). "We observed significantly higher levels of EVs bearing PD-L1, CD40, TNF-RII and/or IL-6Rα in AIDS-NHL cases compared with controls." (PMID 37809067, 2023). "Elevated levels of EVs bearing PD-L1, CD40, TNF-RII and/or IL-6Rα were observed in serum of HIV+ pre-AIDS-NHL cases compared to HIV+ controls." (PMID 37809067, 2023). "We then evaluated any associations between blood circulating EVs expressing the different immune cell surface markers (PD-L1, CD40, CD40L, B7-H3, TNF-RII, IL-6Rα, ICAM-1 or FasL) and tumor subtype of AIDS-NHL patients." (PMID 35655072, 2022). "AIDS-NHL patients showed decreased plasma levels of EVs bearing PD-L1 (p = 0.006), CD40 (p = 0.003), CD40L (p < 0.001) or TNF-RII (p = 0.015) after cancer treatment, compared to baseline plasma levels (Wilcoxon signed rank test)." (PMID 35655072, 2022). "Our results suggest that patients with AIDS-NHL have higher levels of EVs expressing PD-L1, CD40, CD40L or TNF-RII in circulation before cancer treatment and that levels of these EVs are associated with levels of biomarkers of microbial translocation and inflammation." (PMID 35655072, 2022). "Further assessing correlations between EVs and soluble PD-L1 (or soluble forms of CD40, TNF-RII, and IL-6Rα), immunomodulatory cytokines/chemokines, and/or circulating immune cells may elucidate additional factors driving the development of AIDS-NHL." (PMID 37809067, 2023).
chronic kidney disease (10 papers, 2015 to 2024). Impairment of the renal function secondary to chronic kidney damage persisting for three or more months. "Our research has shown that chronic kidney disease (CKD) induces the differentiation of inflammatory CD40+ monocytes through elevated homocysteine levels and DNA methylation." (PMID 39926714, 2024). "Patients with chronic renal failure after hemodialysis had increased CD40+ mononuclear cells in peripheral blood and elevated sCD40L and sCD40 concentrations." (PMID 33202988, 2020). "As the counterpart of the CD40 ligand, the Cd40 gene was also found to be demethylated in inflammatory CD40+ monocytes in the setting of chronic kidney disease." (PMID 33202988, 2020). "We propose that CD40+ MC is a novel pro-inflammatory MC subset and a reliable biomarker for chronic kidney disease severity." (PMID 28738836, 2017). "CD40+ classical/intermediate MC are induced in CVD and further elevated with the progress of chronic kidney disease (CKD)." (PMID 30064449, 2018). "We found increased levels of IL-6, IL-8, CD40, PDL-1, FGF-23, IL-15-RA, TGF-a, and CCL25 that persist at two months after LTA in IKF patients, consistent with current concepts of inflammation as a crucial pathophysiological mechanism in the development of chronic kidney disease." (PMID 39440014, 2024).